E2F3P1 (E2F transcription factor 3 pseudogene 1)
Gene: Processed pseudogene on chromosome 17 (35,490,009 to 35,491,238, forward strand). Ensembl gene ENSG00000267046.
Diseases named in the same sentence as E2F3P1 in open-access papers:
E2F3P1 is named in the same sentence as 6 diseases in open-access papers, as found by Europe PMC text mining. Sharing a sentence is not in itself a finding about the gene and the disease. The quoted sentences say what the papers report.
gastric cancer (2 papers, 2020 to 2021). A primary or metastatic malignant neoplasm involving the stomach. "Three important examples are PTENP1, E2F3P1, and OCT4-pg1 in renal cell carcinoma, hepatocellular carcinoma, and gastric cancer, respectively." (PMID 31947507, 2020).
E2F3P1 also shares sentences with these, for which no sentence is quoted: cancer (1 paper); colon cancer (1); hepatocellular carcinoma (1); liver cancer (1); renal cell carcinoma (1).